CDKN3 (cyclin dependent kinase inhibitor 3)
Diseases named in the same sentence as CDKN3 in open-access papers (continued):
Sharing a sentence is not in itself a finding about the gene and the disease.
breast invasive carcinoma (2 papers, 2019 to 2023). "There was no significance of DNA promoter methylation between invasive breast cancer and normal breast tissues in 4 upregulated hub genes (MAD2L1, FEN1, CDKN3, CCN2)." (PMID 31777591, 2019).
Cirrhosis (2 papers, 2020 to 2021). A chronic disorder of the liver in which liver tissue becomes scarred and is partially replaced by regenerative nodules and fibrotic tissue resulting in loss of liver function. "What’s important, CDKN3 was linked to the activated or inhibited cell cycle modules for the transformation of non-malignancy-associated hepatitis/cirrhosis to HCC." (PMID 33946043, 2021). "This indicates that CDKN3 may be a key gene in the development of HCC in patients with cirrhosis." (PMID 32000807, 2020).
gastric adenocarcinoma (2 papers, 2022 to 2023). "In conclusion, AADAC and CDKN3 genes were significantly upregulated in gastric adenocarcinoma." (PMID 35446856, 2022).
lymph node metastases (2 papers, 2021 to 2024). "Additionally, CDKN3 expression was associated with lymph node metastases in HNSC, KIRC, KIRP, LUAD, LUSC, and PRAD." (PMID 38720365, 2024). "The correlations between the expression level of CDKN3 and lymph node metastasis or clinical staging of ESCC patients are statistically significant." (PMID 34044866, 2021).
thyroid cancer (2 papers, 2021 to 2023). "A previous study demonstrated that ZNF677 inhibits proliferation, migration, and invasion of thyroid cancer cells and exerts its tumor suppressor functions by inhibiting the phosphorylation of AKT via transcriptional repression of its two downstream targets, CDKN3 and HSPB1 (or HSP27)." (PMID 34360599, 2021).
chordoma (1 paper, 2016). Chordomas are rare malignant tumors arising from embryonic remnants of the notochord in axial skeleton. "Second, studies of genetic alterations in chordoma identified mutation or loss of the cell cycle regulator CDKN2A, which is of interest since we identified CDKN2C and CDKN3 as hits in a screen for proteins whose depletion enhances sensitivity to IGF-1R inhibition." (PMID 27200287, 2016).
chronic hepatitis B (1 paper, 2017). "Interestingly, in chronic hepatitis B (CHB), JMJD6 has been shown to promote cluster of differentiation 4 (CD4+) T-cell proliferation by suppressing cyclin-dependent kinase inhibitor 3 (CDKN3) mRNA expression (which is known to inhibit cell cycle progression by binding to CDK2 kinase)." (PMID 28587176, 2017).
dental caries (1 paper, 2012). The decay of a tooth, in which it becomes softened, discolored, and/or porous. "The association signal is centered over a region of low recombination harboring 4 genes, CDKN3, CNIH, GMFB and CGRRF1 (none of which have known or biologically plausible roles in dental caries)." (PMID 23259602, 2012).
gastroenteropancreatic neuroendocrine tumors (1 paper, 2012). "More recently, GTSE1 was identified as one of three cell cycle regulatory genes (along with CDKN3 and Cyclin B1) whose upregulation in gastroenteropancreatic neuroendocrine tumors correlate with metastasis." (PMID 23236459, 2012).
glaucoma (1 paper, 2023). Increased pressure in the eyeball due to obstruction of the outflow of aqueous humor. "On the other hand, Cdkn2c (cyclin-dependent kinase inhibitor 2c) was upregulated in the UON at the three day crush time point, and Cdkn3 (cyclin-dependent kinase inhibitor 3), which prevents the activation of Cdk2, was also increased in early glaucoma in this same region." (PMID 37762022, 2023).
hereditary spastic paraplegia (1 paper, 2016). Hereditary spastic paraplegias (HSP) comprise a genetically and clinically heterogeneous group of neurodegenerative disorders characterized by progressive spasticity and hyperreflexia of the lower limbs. "Mutations in DDHD1 are found in patients with hereditary spastic paraplegia; CDKN3 is linked with different cancers while for FERMT2 and CNIH, no human diseases have been described." (PMID 27757173, 2016).
Obesity (1 paper, 2024). Accumulation of substantial excess body fat. "Genetic variations within CDKN3 have been identified as potential elements that can impact on the risk of developing obesity." (PMID 38918843, 2024).
silicosis (1 paper, 2023). Silicosis is a respiratory disease caused by breathing in (inhaling) silica dust. "In the rat model exposed to silica inhalation for 4 weeks, Bub1, Kifc1, Mcm6, and Prc1 were upregulated in the silicosis group, while Cdkn3 was downregulated." (PMID 37278873, 2023).
tumor (109 papers, 1997 to 2026). "Deletion, mutation, and overexpression of CDKN3 were associated with tumor progression in several cancers." (PMID 36110953, 2022). "As a tumor-promoting gene, CDKN3 encodes a protein that plays an important role in protein phosphorylation and cell cycle regulation." (PMID 35680563, 2022). "We demonstrated that CDKN3 was associated with tumour grade, hepatitis virus infection status, microsatellites, and vascular invasion, by verifying the clinical relevance of CDKN3 in patients with HCC." (PMID 32000807, 2020). "CDKN3 has been suggested to function as a tumor suppressor, and its loss of function was found in a variety of cancers." (PMID 25360622, 2014). "We observed the significant relationship between CDKN3 expression and clinical prognosis, gene mutation, DNA methylation, immune cell infiltration and tumor mutation in a variety of human malignant tumors, trying to help understand the function of CDKN3 in tumors from multiple perspectives." (PMID 38720365, 2024). "In addition to tumor progression, we also found that CDKN3 is associated with lymph node metastasis in six types of tumors." (PMID 38720365, 2024). "Furthermore, CDKN3 has been implicated in tumor progression." (PMID 38720365, 2024). "Interestingly, several spliced transcript variants encoding different isoforms of CDKN3 were found in diverse cancers, implying that these isoforms may be associated with specific tumor formation." (PMID 25360622, 2014). "Module5 (Cell cycle) was characterized by expression of Cell cycle-related genes such as MKI67 and CDKN3 and enrichment of cell cycle, E2F targets and G2M checkpoint pathways, which was considered to be the inception of tumor development." (PMID 40406120, 2025). "Our investigation unveiled diverse expression patterns of the CDKN3 gene within distinct tumor cells." (PMID 38720365, 2024). "Patients in each dataset were grouped into low- and high-CDKN3 expression groups based on tumor CDKN3 mRNA levels as described in the Materials and Methods section." (PMID 38356706, 2024). "CDKN3 plays a crucial role in various cellular processes, such as tumor cell proliferation, DNA replication, cell invasion and migration, and apoptosis." (PMID 38674285, 2024). "We firmly believe that conducting a more comprehensive analysis of the relationship between CDKN3 and the tumor microenvironment holds immense significance for the development of targeted therapies for tumors." (PMID 38720365, 2024). "This further reflects the fact that in the tumor microenvironment, information exchange between cells manifests as a network structure, in which CDKN3 plays a crucial role." (PMID 38720365, 2024). "The relationship between CDKN3 and clinical prognosis is not limited to immune cells in the tumor microenvironment." (PMID 38720365, 2024). "Using the UALCAN and TCGA databases, the DNA methylation levels of CDKN3 between normal and primary tumor tissues were explored." (PMID 38720365, 2024). "With the exception of THCA, we noted higher CDKN3 expression in most tumor tissues compared to paired normal tissues." (PMID 38720365, 2024). "In our study, we elucidated the multifaceted prognostic implications of CDKN3 overexpression on tumor overall survival (OS) based on analyses of TCGA and GEO databases." (PMID 38720365, 2024). "Intriguingly, barring THCA, a consistent trend emerged wherein the majority of tumor tissues demonstrated heightened CDKN3 expression relative to their corresponding normal tissue counterparts." (PMID 38720365, 2024). "We observed significant variations in CDKN3 expression between tumor and normal tissues across TCGA GTEx samples, TCGA samples, and TCGA paired samples." (PMID 38720365, 2024).
tumor (continued). "Through different analyses, we provide examples to demonstrate the feasibility of CDKN3 as a tumor marker." (PMID 38720365, 2024). "In the meantime, tumor size exhibited a connection with CDKN3 expression in ACC, KIRC, KIRP, and LIHC." (PMID 38720365, 2024). "Kaplan-Meier survival analyses show that patients with low tumor CDKN3 mRNA levels have both significantly higher overall and recurrence-free survival probability overtime compared to patients with high CDKN3 levels in all three datasets." (PMID 38356706, 2024). "Through grouping, we attempted to explore the interaction between CDKN3, immune cells, and tumor prognosis." (PMID 38720365, 2024). "Immune correlations suggest that CDKN3 influences tumor immune microenvironment and modulates immune-genes expression." (PMID 37682177, 2023). "Since there are more mitotic cells in rapidly proliferating tumor cells, CDKN3 transcription and protein levels fluctuate throughout the cell cycle, reaching a peak during mitosis." (PMID 37007961, 2023). "CDKN3 is a poor prognostic biomarker in ccRCC that alters many molecular pathways and impacts the tumor immune microenvironment." (PMID 37682177, 2023). "Based on the available data, the impact of CDKN3 upregulation in modulating tumor immune microenvironment is still vague and requires further exploration." (PMID 37682177, 2023). "And the tumour weights in the CDKN3 knockdown group were significantly decreased compared to those in the control group." (PMID 35678231, 2022). "And we demonstrated that ZNF677 plays its tumour suppressor role in RCC through transcriptionally repressing its downstream target CDKN3." (PMID 35678231, 2022). "It is possible that CDKN3 promotes the proliferation of immune cells while promoting the proliferation of tumor cells, so that samples with high expression levels of CDKN3 are more likely to respond to immunotherapy." (PMID 35680563, 2022). "As expected, when OSRC cells with downregulated CDKN3 expression were injected, the xenograft tumour size was significantly reduced compared to the control group." (PMID 35678231, 2022). "The mRNA expression of CDKN3 tended to rise with increasing Gleason score, N stage, T stage, age, residual tumor, and deterioration of therapy outcome." (PMID 35154101, 2022). "To further determine the roles of CDKN3 in tumour‐suppressive effect of ZNF677 on RCC cells, we knocked down CDKN3 in OSRC and CAKI2 cells with ZNF677 deficiency." (PMID 35678231, 2022). "Further, circSDHC promotes ccRCC progression and metastasis by acting as a sponge for miR-127-3p, which is a tumor suppressor that downregulates the activity of CDKN3/E2F1 axis." (PMID 33468140, 2021). "The present study was consistent with later that CDKN3 was a protective factor in tumor development." (PMID 33784984, 2021). "microRNA‐181d‐5p was proved to have tumor‐suppressive effects on non‐small‐cell lung cancer through the CDKN3‐mediated Akt signaling pathway." (PMID 34453499, 2021). "CDKN3 itself is a phosphatase, which acts as a tumor suppressor and mediates the cell cycle by dephosphorylation of cyclin-dependent kinases which mainly include CDK1." (PMID 34795689, 2021). "It was found that CSCs specifically expressed BIRC5, PTTG1, CENPF and CDKN3 genes and presented a scattering distribution in the bulk tumor tissues, which further verified the relatively rare characteristics of CSCs." (PMID 33162821, 2020). "PTPRA and CDKN3 proved to be important for assessing tumor progression in the early and advanced stages." (PMID 33351778, 2020). "Further research indicated CDKN3 seemed to play a role in tumor suppression by CDC2 signaling pathway." (PMID 31886176, 2019).
tumor (continued). "Since rapidly growing tumours have more mitotic cells, the high level of CDKN3 in mitotic phase provides the best plausible explanation for the frequent CDKN3 overexpression in human cancers." (PMID 30517191, 2018). "Statistical analysis showed that a significant enhancement of tumor growth was induced by the knockdown of CDKN3 in K562 cells." (PMID 25360622, 2014). "On the contrary, silencing CDKN3 greatly rendered K562 cells resistant to imatinib-induced apoptosis, and promoted K562 xenografted tumor growth in nude mice." (PMID 25360622, 2014). "In summary, our results reveal that CDKN3 acts as a tumor suppressor during Bcr-Abl-mediated tumorigenesis through control of both cell proliferation and cell survival." (PMID 25360622, 2014). "Statistical analysis revealed that the tumor growth was significantly inhibited by exogenous expression of CDKN3-WT in K562 cells." (PMID 25360622, 2014). "Dual roles of CDKN3 acting either as an oncogene or a tumor suppressor have been documented in different tumors." (PMID 25360622, 2014). "Overexpression of CDKN3 sensitized the K562 leukemic cells to imanitib-induced apoptosis and dramatically inhibited K562 xenografted tumor growth in nude mouse model." (PMID 25360622, 2014). "Overexpression of CDKN3 markedly sensitized K562 leukemic cells to imatinib-induced apoptosis, and inhibited Bcr-Abl-dependent tumor growth in nude mice." (PMID 25360622, 2014). "On the other hand, overexpressed genes like PKP2 and CDKN3 may promote tumor progression by affecting calcium-dependent cell-cell adhesion and cell cycle regulation, respectively." (PMID 40433361, 2025). "In addition to the prognosis and CDKN3 expression of 17 types of tumors analyzed by TCGA, we also found a correlation between CDKN3 expression and tumor size in ACC, KIRC, KIRP, and LIHC." (PMID 38720365, 2024). "Furthermore, we also obtained alterations in CDKN3 expression levels at distinct tumor stages by the utilization of the UALCAN online tool." (PMID 38720365, 2024). "The ability of olmutinib to decrease CDKN3 expression could be a valuable therapeutic mechanism, potentially contributing to the inhibition of tumor growth and progression." (PMID 38674285, 2024). "As a cell cycle-regulating factor, CDKN3 may open up a new avenue for tumor therapy by determining its role in different tumors." (PMID 39689117, 2024). "In summary, we can confirm that the presence of CDKN3 predicts poor tumor prognosis." (PMID 38720365, 2024). "Collectively, these analyses provided a comprehensive framework for understanding the biological significance of CDKN3 in the context of tumors, unraveling its involvement in vital cellular processes, molecular interactions, and pathways that influence tumor development and progression." (PMID 38720365, 2024). "Additionally, ESCA, KIRC, LUSC, and PAAD tumor tissues had considerably higher levels of CDKN3 methylation expression." (PMID 38720365, 2024). "It is worth considering whether CDKN3 is related to certain aspects of tumor cell renewal and proliferation?" (PMID 38720365, 2024). "However, there remains a dearth of research analyzing the suitability of CDKN3 as a tumor marker from a macro perspective." (PMID 38720365, 2024). "A variety of studies found that CDKN3 played a crucial role in tumor progression." (PMID 37682177, 2023). "In addition, ZNF677 exerted its tumour suppressor functions in RCC cells through transcriptional repression of CDKN3 via binding to its promoter." (PMID 35678231, 2022). "CDKN3 plays a key role in regulating the cell cycle and tumor progression." (PMID 36471446, 2022). "The role of CDKN3 has been controversial in tumor progression." (PMID 33784984, 2021). "The CDKN3 gene inhibits tumor growth by controlling mitosis, which is a tumor suppressor gene." (PMID 32047745, 2020).
tumor (continued). "Some studies have shown that CDKN3 acts as a cancer-promoting gene in a variety of ways to regulate the G1/S phase transition, while others have reported that CDKN3 plays an anti-tumour role via dephosphorylation of CDK2, thereby inhibiting the G1/S phase transition." (PMID 32000807, 2020). "The highly expression of CDKN3 in human cancer tissue may reflect the increased proportion of mitotic cells in the tumor." (PMID 33178836, 2020). "It is well known that CDKN3 is overexpressed in multiple human tumor tissues and cell lines." (PMID 33178836, 2020). "Although we cannot disregard the role of CDKN3 in tumor migration and invasion, the partial inhibition of CDKN3 expression (35–50%) suggests its involvement in tumor progression may be by inducing cell proliferation through a direct action on the cell cycle." (PMID 26372210, 2015). "Based on the study results, we can conclude that the CDKN3 mRNA expression level might be a good predictive marker for evaluating patient survival and tumor aggressiveness." (PMID 26372210, 2015). "Tang claimed that CDKN3 has significant biological implications in tumor pathogenesis." (PMID 25866773, 2015). "We can also conclude that the CDKN3 gene, at the mRNA level, could be a good therapeutic target for tumor growth inhibition." (PMID 26372210, 2015). "On the other hand, as CDKN3 seems to be indispensable for cancer cell proliferation, it could be a good therapeutic target for tumor growth inhibition." (PMID 26372210, 2015). "Here we found that CDKN3 acts as a tumor suppressor in Bcr-Abl-mediated leukemogenesis." (PMID 25360622, 2014). "As hypothesized, we found that silencing CDKN3 expression greatly promoted K562 xenografted tumor growth in nude mice." (PMID 25360622, 2014). "Here we found that CDKN3 acted as a tumor suppressor in Bcr-Abl-induced tumorigenesis." (PMID 25360622, 2014). "While more work is needed to dissect the role of the CDKN3 in cancer, these findings suggest that CDKN3 may potentially function either as an oncogene or a tumor suppressor." (PMID 25360622, 2014). "In addition, we found that CDKN3 mutant (CDKN3-C140S) devoid of the phosphatase activity failed to affect the K562 leukemic cell survival and xenografted tumor growth, suggesting that the phosphatase of CDKN3 was required for its tumor suppressor function." (PMID 25360622, 2014). "Therefore, we speculate that high levels of CDKN3 may interfere with the prognosis of tumor patients by affecting immune cells." (PMID 38720365, 2024). "Moreover, the role of CDKN3 in the tumor microenvironment has begun to emerge." (PMID 38720365, 2024). "Therefore, using CDKN3 as a tumor treatment target will be very important." (PMID 38720365, 2024). "Increasing evidences suggest that CDKN3 could promote tumor progression." (PMID 33784984, 2021). "CDKN3 knockout experiments indicated that CDKN3 could inhibit tumor growth." (PMID 32047745, 2020). "CDKN3 depletion impairs SCC cell progression into S-phase and reduces tumor growth in xenograft models." (PMID 41876816, 2026). "The CDKN3 methylation expression levels in HNSC and TGCT tumor tissues were significantly down-regulated." (PMID 38720365, 2024). "Our study also found that the methylation expression level of CDKN3 in HNSC and TGCT tumor tissues is significantly lower than that in normal tissues." (PMID 38720365, 2024). "Apart from SKP2, ITGB4, CDKN3, TFGP1, SLCO1B3, CDX2 and KIF18A, the remaining model genes showed significant correlations with stem cell score, immune score and tumour microenvironment." (PMID 39656479, 2024).